KRTAP4-5 (keratin associated protein 4-5)
Description:
In the hair cortex, hair keratin intermediate filaments are embedded in an interfilamentous matrix, consisting of hair keratin-associated proteins (KRTAP), which are essential for the formation of a rigid and resistant hair shaft through their extensive disulfide bond cross-linking with abundant cysteine residues of hair keratins. The matrix proteins include the high-sulfur and high-glycine-tyrosine keratins.
Synonyms: KAP4.5; KRTAP4.5
Tractability: No criterion of Open Targets' tractability assessment is met for any kind of drug.
Gene: Protein-coding gene on chromosome 17 (41,148,924 to 41,149,825, reverse strand). Ensembl gene ENSG00000198271.
Pathways (Reactome):
Developmental Biology: Keratinization
Gene Ontology:
Molecular function: protein binding
Biological process: hair cycle
Cellular component: cytosol; keratin filament
Genetic constraint (gnomAD): Loss-of-function variants: 0 observed, 1.15 expected, observed/expected ratio (o/e) 0, 90% interval 0 to 1.68. That is too few expected variants to judge how well the gene tolerates losing a copy. Missense variants: 159 observed, 189.12 expected, observed/expected ratio (o/e) 0.84, 90% interval 0.74 to 0.96. Synonymous variants: 65 observed, 68.49 expected, observed/expected ratio (o/e) 0.95, 90% interval 0.78 to 1.17.
Homologues: Orthologues: chimpanzee KRTAP4-5 (95% identical), rat LOC120098854 (49% identical), rat Krtap10-9 (48% identical), rat Krtap10-1 (48% identical), mouse Krtap5-24 (45% identical), mouse Krtap10-33 (44% identical), rat Krtap10-1l1 (44% identical), mouse Krtap10-21 (43% identical), mouse Krtap10-25 (43% identical), mouse Krtap10-29 (43% identical), mouse Krtap10-32 (43% identical), mouse Krtap10-22 (43% identical), and 25 more. Paralogues in human: KRTAP4-12 (85% identical), KRTAP4-11 (83% identical), KRTAP4-6 (81% identical), KRTAP4-9 (76% identical), KRTAP4-8 (73% identical), KRTAP4-3 (70% identical), KRTAP4-7 (69% identical), KRTAP4-4 (64% identical), KRTAP4-2 (59% identical), KRTAP4-1 (51% identical), KRTAP10-7 (49% identical), KRTAP10-9 (48% identical), and 35 more.
Diseases named in the same sentence as KRTAP4-5 in open-access papers:
KRTAP4-5 is named in the same sentence as 4 diseases in open-access papers, as found by Europe PMC text mining. Sharing a sentence is not in itself a finding about the gene and the disease. The quoted sentences say what the papers report.
adenoma (3 papers, 2018 to 2025). A neoplasm arising from the epithelium. "APC is the gene most frequently mutated in conventional colon adenomas; four genes recurrently mutated in adenomas CTNNB1 (catenin-β1), KRTAP4-5 (keratin-associated protein 4–5), GOLGA8B (golgin A8 family member B) and TMPRSS13 (transmembrane protease, serine 13) had the oncogene pattern." (PMID 29652830, 2018). "Lin and colleagues characterized the mutational alterations using WES and proposed four genes (CTNNB1, KRTAP4-5, GOLGA8B, and TMPRSS13) as the potential somatic drivers in conventional adenomas." (PMID 40757636, 2025).
tumor (1 paper, 2017). "We identified four novel genes, KRTAP4-5, OR2T35, GPRIN1, and MRPL18, of unknown function in tumor progression and metastasis." (PMID 28249600, 2017).
KRTAP4-5 also shares sentences with these, for which no sentence is quoted: colon adenoma (1 paper); hypopharyngeal carcinoma (1).